CHTOP (chromatin target of PRMT1)
Description:
Plays an important role in the ligand-dependent activation of estrogen receptor target genes. May play a role in the silencing of fetal globin genes. Recruits the 5FMC complex to ZNF148, leading to desumoylation of ZNF148 and subsequent transactivation of ZNF148 target genes (By similarity). Plays an important role in the tumorigenicity of glioblastoma cells. Binds to 5-hydroxymethylcytosine (5hmC) and associates with the methylosome complex containing PRMT1, PRMT5, MEP50 and ERH. The CHTOP-methylosome complex associated with 5hmC is recruited to selective sites on the chromosome, where it methylates H4R3 and activates the transcription of genes involved in glioblastomagenesis. Required for effective mRNA nuclear export and is a component of the TREX complex which is thought to couple mRNA transcription, processing and nuclear export, and specifically associates with spliced mRNA and not with unspliced pre-mRNA. TREX is recruited to spliced mRNAs by a transcription-independent mechanism, binds to mRNA upstream of the exon-junction complex (EJC) and is recruited in a splicing- and cap-dependent manner to a region near the 5' end of the mRNA where it functions in mRNA export to the cytoplasm via the TAP/NFX1 pathway. The TREX complex is essential for the export of Kaposi's sarcoma-associated herpesvirus (KSHV) intronless mRNAs and infectious virus production. Stimulates DDX39B ATPase and helicase activities. In cooperation with ALYREF/THOC4 enhances NXF1 RNA binding activity.
Synonyms: SRAG; C1orf77; FOP; PP7704; DKFZP547E1010; C10orf77; FL-SRAG; SRAG-3; SRAG-5
Tractability: PROTAC: UniProt records ubiquitination sites on it; ubiquitination databases record sites on it; its protein half-life has been measured.
Gene: Protein-coding gene on chromosome 1 (153,633,982 to 153,646,306, forward strand). Ensembl gene ENSG00000160679.
Subcellular location: Nucleus; Nucleus, nucleolus; Nucleus, nucleoplasm; Nucleus speckle
Subcellular location (Human Protein Atlas): Nuclear speckles
Pathways (Reactome):
Metabolism of RNA: Transport of Mature mRNA derived from an Intron-Containing Transcript; mRNA 3'-end processing
Gene Ontology:
Molecular function: methyl-CpG binding; protein binding; RNA binding
Biological process: chromatin remodeling; mRNA export from nucleus; positive regulation of ATP-dependent activity; positive regulation of helicase activity
Cellular component: nuclear speck; nucleus; transcription export complex; nucleoplasm; nucleolus
Genetic constraint (gnomAD): Loss-of-function variants: 18 observed, 34.74 expected, observed/expected ratio (o/e) 0.52, 90% interval 0.36 to 0.77. The upper end of that interval is the gene's LOEUF score, 0.77, which puts it in group 3 of 6, group 1 being the genes least tolerant of losing a copy. Missense variants: 263 observed, 350.69 expected, observed/expected ratio (o/e) 0.75, 90% interval 0.68 to 0.83. Synonymous variants: 117 observed, 133.04 expected, observed/expected ratio (o/e) 0.88, 90% interval 0.76 to 1.02.
Homologues: Orthologues: chimpanzee CHTOP (100% identical), macaque CHTOP (99% identical), pig CHTOP (99% identical), mouse Chtop (99% identical), dog CHTOP (99% identical), guinea pig CHTOP (99% identical), rat Chtop (98% identical), rat Chtopl1 (80% identical), tropical clawed frog chtop (71% identical), zebrafish chtopa (69% identical), zebrafish chtopb (38% identical), Caenorhabditis elegans aly-3 (17% identical), and 1 more. Paralogues in human: ALYREF (27% identical), POLDIP3 (18% identical).
Diseases named in the same sentence as CHTOP in open-access papers:
CHTOP is named in the same sentence as 18 diseases in open-access papers, as found by Europe PMC text mining. Sharing a sentence is not in itself a finding about the gene and the disease. The quoted sentences say what the papers report.
glioblastoma (8 papers, 2015 to 2025). The most malignant astrocytic tumor (WHO grade IV). "Methylation of CHTOP promotes 5FMC recruitment, this complex then interacts with the methylosome to regulate the expression of glioblastoma promoting genes." (PMID 39480826, 2024). "Dysregulation at the cellular level of CHTOP has been shown however, to play an important role in the tumorigenicity of glioblastoma cells, as well as being a critical regulator of γ-globin gene expression." (PMID 36061196, 2022). "A recent study reported that CHTOP was recruited to 5-hydroxymethylcytosine-containing DNA sequences and involved in the tumorigenicity of glioblastoma, which suggests that CHTOP may be a potential therapeutic target for cancer therapy." (PMID 31380263, 2019). "Knockdown of CHTOP inhibits tumorigenicity of glioblastoma cells resulting in longer mice survival, pointing to the importance of 5hmC levels for the prognosis of patients with proneural glioblastoma tumors." (PMID 31311166, 2019). "Excitingly, WT1 and CHTOP share binding affinity for the same promoter sequence, implicating WT1 as a strong contender for influencing sustained pathogenic transcriptional signaling in glioblastoma." (PMID 29623275, 2018).
diabetes (3 papers, 2020 to 2025). "We identified an intragenic CpG site in the gene encoding chromatin target of PRMT1 (CHTOP) that exhibits complementary tissue specificity to INS and may be used to increase confidence of detecting islet damage in youth with prediabetes and diabetes." (PMID 32736653, 2020). "Other approaches focusing on liquid biopsy biomarkers for the management of diabetes have examined methylation of INS, IAPP and GCK either as single parameters or as combined parameters, i.e., INS and CHTOP in a duplex assay." (PMID 35207316, 2022).
ovarian carcinoma (3 papers, 2019 to 2022). A malignant neoplasm originating from the surface ovarian epithelium. "We found that higher expression of CHTOP was associated with a lower disease-free survival (DFS) rate in ovarian cancer patients." (PMID 30910850, 2019). "In contrast, CHTOP silence significantly decreased the number of spheres in those two cell lines as compared with the corresponding si-con group, indicating that CHTOP overexpression is closely associated with an enhanced stemness in epithelial ovarian cancer." (PMID 30910850, 2019). "Our results showed that highly expressed CHTOP in ovarian cancer tissues was associated with an advanced stage and poor progression-free survival (PFS) in patients." (PMID 31380263, 2019). "In the present study, we demonstrated the associations of CHTOP with the malignant behaviors of epithelial ovarian cancer cells." (PMID 30910850, 2019). "In the present study, we investigated the association of CHTOP expression with clinical outcomes and explored its role in the malignant behaviors of epithelial ovarian cancer cells." (PMID 30910850, 2019). "Results from IHC and bioinformatic analysis showed CHTOP was highly expressed in human ovarian cancer tissues and associated with a poor progression-free survival in patients." (PMID 31380263, 2019). "The results from Kaplan–Meier analysis showed that higher expression of CHTOP was associated with a significantly lower 10-year DFS rate in ovarian cancer patients (P<0.001)." (PMID 30910850, 2019). "Hypothesizing that CHTOP may play an important role in the tumorigenic ability of epithelial ovarian cancer cells, we also investigated the association of CHTOP with epithelial ovarian cancer stemness." (PMID 30910850, 2019). "Hypothesizing that CHTOP may play an important role in epithelial ovarian cancer chemoresistance, we next investigated the association of CHTOP with epithelial ovarian cancer cell chemosensitivity." (PMID 30910850, 2019). "Since OV-90 and SK-OV-3 are characterized by a higher expression of CHTOP, we next compared the migration and invasion ability of OV-90 and SK-OV-3 with IGROV-1 in order to investigate if CHTOP is associated with the migration or invasion capability of epithelial ovarian cancer cells." (PMID 30910850, 2019). "Moreover, Kaplan–Meier analysis showed that the high expression of CHTOP in ovarian cancer tissues was associated with a lower PFS rate in patients." (PMID 31380263, 2019). "Furthermore, we demonstrated that the high expression of CHTOP was associated with a lower PFS rate in ovarian cancer patients using online survival dataset." (PMID 31380263, 2019). "Subsequently, si-CHTOP was used to investigate the role of CHTOP in the migration and invasion capability of epithelial ovarian cancer cells." (PMID 30910850, 2019). "To start the study of the role of CHTOP in epithelial ovarian cancer, we first screened the si-CHTOP that can effectively silence the protein expression of CHTOP." (PMID 30910850, 2019). "As stemness has been considered as a critical mechanism underlying cancer metastasis and relapse, we, thus, also investigated the role of CHTOP in epithelial ovarian cancer stemness." (PMID 30910850, 2019). "The higher expression of CHTOP was specifically observed in epithelial ovarian cancer cells, which makes it possible to use CHTOP-targeted therapy in epithelial ovarian cancer with normal cells largely unaffected." (PMID 30910850, 2019). "In the present study, we investigated the correlation between tumor-derived CHTOP expression and prognosis and explored its role in the malignant behaviors of epithelial ovarian cancer cells." (PMID 30910850, 2019). "The staining intensity score of CHTOP in malignant or metastatic ovarian cancer tissues was significantly higher than that in normal, adjacent, or benign tissues." (PMID 31380263, 2019).
ovarian carcinoma (continued). "Since high expression of CHTOP was found in metastatic human ovarian cancer cell lines and tissues, we then also detected the invasion and migration ability of cisplatin-resistant EOC cells." (PMID 31380263, 2019). "Next, si-CHTOP was employed to investigate the role of CHTOP in epithelial ovarian cancer cisplatin-resistance." (PMID 30910850, 2019). "In the present study, we first investigated the correlation of high expression of CHTOP with clinical outcomes in ovarian cancer." (PMID 30910850, 2019). "CHTOP knockdown reduced the migration and the invasion of malignant ovarian cancer cell lines." (PMID 35418993, 2022). "In addition, animal study is desired to further assess the therapeutic value of CHTOP inhibition in epithelial ovarian cancer." (PMID 30910850, 2019). "Also, CHTOP was highly expressed in human ovarian cancer tissues compared with normal and adjacent tissues." (PMID 30910850, 2019). "Furthermore, compared with the IGROV-1 cell line, SK-OV-3 (malignant epithelial ovarian cancer cell line), and OV-90 (metastatic epithelial ovarian cancer cell line) cell lines showed a much higher expression of CHTOP." (PMID 30910850, 2019). "Therefore, in our study, we examined the role of CHTOP in epithelial ovarian cancer metastasis." (PMID 30910850, 2019). "More importantly, we also found a much higher expression of CHTOP in human metastatic and malignant EOC tissues as compared to normal ovary tissues, adjacent tissues, or benign tumor tissues, suggesting that CHTOP might be a potential specific target for advanced ovarian cancer." (PMID 31380263, 2019). "In summary, we demonstrate for the first time that CHTOP is a novel biomarker associated with chemoresistance, stemness, and metastasis in chemoresistant EOC which is promising in overcoming EOC chemoresistance as a molecular target and predicting ovarian cancer prognosis as a clinical indicator." (PMID 31380263, 2019). "The data from immunoblot and immunofluorescence showed that, compared with normal epithelial ovarian cell HOSE, epithelial ovarian cancer cell lines (IGROV-1, SK-OV-3, and OV-90) were characterized by a significantly higher intracellular expression of CHTOP." (PMID 30910850, 2019). "Although patients with higher expression of CHTOP in ovarian cancer tissues showed a lower 10-year OS, the difference was not significant (P=0.083)." (PMID 30910850, 2019). "However, the role of CHTOP in epithelial ovarian cancer is not clear yet." (PMID 30910850, 2019).
Lynch syndrome (1 paper, 2024). An autosomal dominant hereditary neoplastic syndrome characterized by the development of colorectal carcinoma and a high risk of developing endometrial carcinoma, gastric carcinoma, ovarian carcinoma, renal pelvis carcinoma, and small intestinal carcinoma. "The gene ontologies for list 7- linked CHTOP, ADNP, HLTF, WAPL, ZMYM4, and ZNF146 to Lynch Syndrome." (PMID 39480826, 2024). "We propose that ADNP, CHTOP, HLTF, MTF2, WAPL, and ZMYM4 are novel genes in Lynch Syndrome." (PMID 39480826, 2024).
retinoblastoma (1 paper, 2024). A malignant tumor that originates in the nuclear layer of the retina. "The gene ontologies for list 6- linked CHTOP, FXR1, and REST to Retinoblastoma." (PMID 39480826, 2024). "We propose that CHTOP, FXR1, and REST are novel genes in Retinoblastoma." (PMID 39480826, 2024).
Sepsis (1 paper, 2020). Sepsis is defined as life-threatening organ dysfunction caused by a dysregulated host response to infection. "Compared to controls, subjects with sepsis exhibited elevations in methylated INS and CHTOP-817 DNA levels but not the corresponding unmethylated DNA levels." (PMID 32736653, 2020).
cancer (3 papers, 2015 to 2019). A tumor composed of atypical neoplastic, often pleomorphic cells that invade other tissues. "Based on our current results, it is worthwhile deeply investigating the regulative role of CHTOP in cancer therapeutic resistance and metastasis." (PMID 31380263, 2019). "This study sheds light on the role of CHTOP in cancer and makes it an attracted target for cancer treatment." (PMID 30910850, 2019). "Further results from immunoblot suggest that CHTOP knockdown not only decreased the protein expressions of two representative surface markers of cancer stem cell (CD44 and ALDH1) but also inhibited the protein expressions of two important transcriptional makers of cancer stem cell (SOX-2 and NANOG)." (PMID 30910850, 2019). "Additionally, CHTOP silence also remarkably weakened the stemness of OV-90 and SK-OV-3 through inhibiting the protein expressions of several transcriptional or surface markers of cancer stem cells." (PMID 30910850, 2019). "Thus, it is possible that Omomyc may affect the PRMT1/PRMT5/MEP50/CHTOP complex, impairing cancer-related gene expression." (PMID 26563484, 2015). "However, the mechanisms underlying CHTOP in regulating cancer metastasis, apoptosis, and stemness remain unclear and no further studies can be referenced." (PMID 30910850, 2019). "Furthermore, as CSC marker expression is crucial evidence for evaluating cancer stemness, we also investigated which CSC markers were affected by CHTOP KD." (PMID 31380263, 2019).
tumor (3 papers, 2016 to 2019). "CHTOP is also required for the expression of key genes required for the maintenance of tumor cells in glioblastoma." (PMID 27679854, 2016). "Animal study is warranted to test whether CHTOP KD can inhibit tumor growth and promote chemosensitization." (PMID 31380263, 2019). "CHTOP is recruited to the pS2 promoter, inducing the expression of estrogen target genes in breast cancer cells and thereby maintaining growth of the tumor." (PMID 27679854, 2016).
CHTOP also shares sentences with these, for which no sentence is quoted: asthma (1 paper); atherosclerosis (1); benign tumor (1); bipolar disorder (1); Hepatitis B (1); Hepatitis C (1); Impaired glucose tolerance (1); Obesity (1); pulmonary fibrosis (1); schizophrenia (1).